CASP9 (caspase 9)
Diseases named in the same sentence as CASP9 in open-access papers (continued):
Sharing a sentence is not in itself a finding about the gene and the disease.
colorectal cancer (55 papers, 2004 to 2026). A primary or metastatic malignant neoplasm that affects the colon or rectum. "As reported in the literature, 5-FU initiates apoptosis in colorectal cancer through the activation of caspase-9 and causes the death of cells after the induction of caspase-3." (PMID 37368241, 2023). "Several apoptotic signalling proteins such as Bax, Caspase 3, Cox 2 and Caspase 9 are known to be associated with colorectal cancer (CRC)." (PMID 32884209, 2020). "Based on these results, we propose that erastin binds to VDAC1 to disrupt normal mitochondrial function, causing mPTP opening, and eventually leading to caspase-9-dependent apoptosis activation in colorectal cancer cells." (PMID 27171435, 2016). "The relationship between CASP9 and colorectal cancer remains poorly understood, and studying its association with clinicopathological features and survival could provide valuable insights for predicting outcomes and guiding treatment strategies." (PMID 39940328, 2025). "To further address the apoptotic effect of CAP on various colorectal cancer cells, we analyzed cleaved caspase-9 and cleaved caspase-3 levels." (PMID 38351129, 2024). "Combined ABT-737/AZ’1569 treatment resulted also in potent increases in apoptosis as indicated by increased PARP cleavage and caspase-9/8/3 processing in all KRASG12CMT colorectal cancer cells." (PMID 36279564, 2023). "miR-23a, miR-24a, and miR-582-5p reportedly function in colorectal cancer and glioblastoma by regulating CASP9." (PMID 36552744, 2022). "Mechanically, we found that AB4 enhanced colorectal cancer cell apoptosis through Src-dependent caspase-9 apoptotic pathway." (PMID 34890366, 2021). "Caspase 9 (CASP9) can target colorectal cancer stem cells by inducible CASP9 to decrease the tumor size." (PMID 34938319, 2021). "Previous reports identified Src kinase phosphorylated caspase-9 to enhance its apoptotic activity, which was a promising novel strategy for chemotherapy resistance reversal in colorectal cancer." (PMID 34890366, 2021). "AB4 sensitizes colorectal cancer to 5-FU-based chemotherapy by elevated Src activation and caspase-9 apoptotic pathway." (PMID 34890366, 2021). "More importantly, AB4 sensitizes human colorectal cancer to fluorouracil-based chemotherapy through Src-dependent caspase-9 apoptotic pathway." (PMID 34890366, 2021). "A significant decrease in caspase-9 activity and concomitant overexpression of caspase-8 was found in tissues obtained from patients with colorectal cancer compared to tissues obtained from healthy individuals." (PMID 33919909, 2021). "Activation of caspase-8 and caspase-9 led to activation of caspase-3, caspase-6, and caspase-7 and resulted in apoptosis of colorectal cancer cells." (PMID 33953834, 2021). "TRAF3 also plays pro-apoptotic roles in human bladder and colorectal carcinoma cells upon CD40 ligation via BAX/BAK-caspase 9- and ROS- dependent mechanisms." (PMID 34745083, 2021). "Mechanistically, Sur-X induced Caspase 9-dependent intrinsic apoptosis in colorectal cancer cells by disrupting the survivin-XIAP complex and subsequently destabilizing survivin and XIAP." (PMID 32381104, 2020). "Together, these results indicated that the disruption of survivin-XIAP complex by Sur-X caused ubiquitination-mediated degradation of survivin and XIAP, and subsequently promoted Caspase 9-dependent intrinsic apoptosis in colorectal cancer cells." (PMID 32381104, 2020). "The first aim was to obtain evidence for the actual expression of Bcl2, Bad, BAX, caspase-8, and caspase-9 in pancreatic and colorectal carcinoma cells." (PMID 30686270, 2019). "Expression of phosphorylated AKT and phosphorylated caspase-9 are significantly correlated in gastric and colorectal cancer." (PMID 27798717, 2017). "Here, we provide evidences that miR-27a antioligonucleotides sensitize colorectal cancer stem cells to TRAIL by promoting the formation of Apaf-1-caspase-9 complex." (PMID 28423356, 2017).
colorectal cancer (continued). "In two other colorectal cancer cell lines, erastin (10 μM) also induced caspase-9 and apoptosis activation as well as ROS production." (PMID 27171435, 2016). "In the present study, we demonstrated that erastin exerted potent cytotoxic effect against multiple human colorectal cancer cells possibly via inducing oxidative stress and caspase-9 dependent cell apoptosis." (PMID 27171435, 2016). "Our in vitro studies showed that erastin exerted potent cytotoxic effects against multiple human colorectal cancer cell lines, possibly via inducing oxidative stress and caspase-9 dependent cell apoptosis." (PMID 27171435, 2016). "Here, we found that activation of Hsp27 inhibited cleavage of caspase 9 and 3 in the TICs of colorectal cancer." (PMID 23185379, 2012). "Transcripts specific to co-stimulatory molecules (CD80 and CD86), HSP60, MHC peptides, pro-inflammatory cytokine receptors, Perforin 1 and Caspase 9 were amongst those that were up-regulated in MSI-H colorectal cancers." (PMID 15298707, 2004). "The activity level of the apoptosis-associated markers (CASP9 and CASP10) may help assess the prognosis for patients with stage II colorectal cancer." (PMID 38674831, 2024). "Furthermore, 5-FU has been shown to be a pro-apoptotic agent in colorectal cancer cells by activating caspase 9, which contributes to caspase-3 activation." (PMID 37504320, 2023). "Moreover, it is able to elicit apoptosis in colorectal cancer cells by cytochrome c release and caspase 9 and caspase 3 stimulation." (PMID 36810432, 2023). "An analysis of apoptotic gene expression in human colorectal carcinoma cells (HCT-15) after treatment with a crude mixture of saponins from Panax ginseng C.A. Meyer revealed a high level of proapoptotic genes, including those encoding caspase 9 and Bax." (PMID 37447047, 2023). "Mechanically, AB4 activated caspase-9 pathway in 5-FU resistant colorectal cancer cells." (PMID 34890366, 2021). "However, the expression of caspase-8 and caspase-9 was evaluated in patients with colorectal cancer." (PMID 33919909, 2021). "Moreover, Src-caspase-9 signaling was a promising target for colorectal cancer stem cell elimination." (PMID 34890366, 2021). "As the first peptide that targets the survivin-XIAP complex, Sur-X was proved to be able to interfere with survivin-XIAP interaction, promote ubiquitination-mediated degradation of survivin and XIAP, and hence induce Caspase 9-dependent intrinsic apoptosis in colorectal cancer cells." (PMID 32381104, 2020). "However, exposure of human colorectal carcinoma cells HCT-116 to proanthocyanidins from the same source significantly upregulated mRNAs encoding caspase-2, caspase-3 and caspase-9." (PMID 31752295, 2019). "In line with our findings, a study that used a nano-chitosome form of OP on the colorectal cancer cell line HT-29 found that treatment with nano-chitosome-OP induced apoptosis (verified by AO/PI staining) by increasing the expression of caspase-3 and caspase-9." (PMID 41509117, 2025). "For this purpose, the relative expression of CASP3, CASP9, BCL2, and BCL2L11 was quantified in colorectal cancer DLD-1 and SW620 cells treated with 7 mg/mL of the extract for 72 h." (PMID 40298626, 2025). "Knockdown of microRNA-27a increased the expression level of Apaf-1, thus enhancing the formation of Apaf-1-caspase-9 complex and subsequently promoting the TRAIL-induced apoptosis in colorectal cancer stem cells." (PMID 28423356, 2017). "It was recently shown that mRNA expressions of Caspase-9 and Caspase-3 (unlike Caspase-8) were downregulated in human colorectal cancer tissues in comparison to marginal tissues." (PMID 37108361, 2023). "In colorectal cancer HCT-15 cells, TSAIII treatment was found to induce apoptosis, as demonstrated by the activation of caspase, induction of cleaved-caspase-3, caspase-8, and caspase-9, and decreased expression of Bcl-xL and Bcl-2." (PMID 36611961, 2022).
colorectal cancer (continued). "In addition, caspase-9 was activated in HT-29 and HCT 116 colorectal cancer cells, eventually leading to translocation of Bax from the cytosol to mitochondria to induce apoptosis." (PMID 29221182, 2017). "Also, salinomycin induces apoptosis in cisplatin-resistant human colorectal cancer cells (Cisp-resistant SW620 cells) by increasing the protein expression of caspases 3, caspase 8, caspase 9 and BAX, but decreasing the protein expression of Bcl-2." (PMID 25531367, 2014). "Furthermore, it was reported that HEFPs markedly increase the levels of reactive oxygen species in colorectal cancer cells (HCT-116 and DLD-1), leading to apoptosis via a caspase-9-dependent mitochondrial intrinsic pathway and thereby providing an effective treatment modality for colorectal cancer." (PMID 40333844, 2025).
ovarian carcinoma (49 papers, 2007 to 2025). A malignant neoplasm originating from the surface ovarian epithelium. "EGFR is not only associated with poor prognosis in ovarian cancer it also promotes alternative splicing of Caspase-9 in favor of Caspase-9b." (PMID 22860069, 2012). "Recent research has shown that ovarian cancer cell death is associated with the activation of caspase-1, caspase-3, and caspase-9." (PMID 21526214, 2011). "In this study, hydnocarpin induced ovarian cancer cell apoptosis by activating the caspase-9-dependent intrinsic pathway mediated via ROS production." (PMID 40722951, 2025). "In ovarian cancer, campesterol also activated cell death signals, such as cleaved caspase 3, cleaved caspase 9, cytochrome c, BAX, and BAK." (PMID 33802602, 2021). "Serum levels of caspase-3, caspase-8, caspase-9, and CA 125 antigen were determined in healthy women belonging to the control group and women with ovarian cancer." (PMID 33919909, 2021). "The aim of this study was to analyze the soluble markers monitoring the apoptosis process by assessing the levels of caspase-3, caspase-8, and caspase-9 in the serum of women with ovarian cancer." (PMID 33919909, 2021). "Splicing factor SFPQ regulated alternative splicing of caspase-9 mRNA and was involved in ovarian cancer sensitivity to platinum." (PMID 34966670, 2021). "The aim of this study was to evaluate serum levels of caspase-3, caspase-8, and caspase-9 in women with ovarian cancer." (PMID 33919909, 2021). "In women with ovarian cancer, the mean caspase-9 concentration was 4.02 ± 1.88 ng/mL ranging from 1.40 ng/mL to 8.30 ng/mL and was significantly reduced compared to the control group (p ˂ 0.001)." (PMID 33919909, 2021). "Next, the mean serum caspase-9 levels in women were examined, taking into account the type of ovarian cancer diagnosed." (PMID 33919909, 2021). "In this study, DMU-214 was found to increase initiator casp-9 and executive casp-3/7 activity in A-2780 ovarian cancer cells." (PMID 27585955, 2016). "The experiments showed that ovarian cancer cells treated with the synthetic stilbene exhibited upregulated activity of initiator caspase-9 and effector caspase-3." (PMID 26229578, 2015). "Cleaved-caspase-3 and cleaved-caspase-9 expression levels were dramatically upregulated following PMBPs treatment in ovarian cancer cells (p<0." (PMID 26539720, 2015). "Fenretinide is also reported to activate caspase-8 and caspase-9 in glioblastoma, meningioma and ovarian carcinoma." (PMID 20877355, 2010). "In addition, cleavage and activation of ER stress-induced apoptosis-specific caspase-12, mitochondrial apoptosis-specific caspase-9 and the major effector caspase caspase-3 were higher in hyptolide-treated ovarian cancer cells." (PMID 40506749, 2025). "Therefore, the aim of the present study was to evaluate serum levels of caspase-3, caspase-8, and caspase-9 in women with ovarian cancer." (PMID 33919909, 2021). "Furthermore, RSV upregulated the expression of caspase-9 and caspase-3 in an implanted human primary ovarian cancer cell (SKOV3) in nude mice." (PMID 32244860, 2020). "In summary, our results demonstrate that C. militaris triggers TNF-α/TNFR1-mediated apoptosis by suppressing the NF-κB signaling pathway and promotes the cleavage of caspase-3 and caspase-9 through the induction of the extrinsic apoptotic pathway in ovarian cancer cells." (PMID 32020859, 2020). "Furthermore, drug-resistant ovarian cancer cells treated with gliotoxin followed by paclitaxel exhibited activation and cleavage of caspase-9, caspase-3, and PARP." (PMID 31336860, 2019). "In addition, (−)-asarinin increased the activation of caspase-3, caspase-8, and caspase-9 in ovarian cancer cells." (PMID 30044423, 2018). "To confirm our hypothesis that KP extract induces apoptosis in ovarian cancer cells, we specifically analyzed the key apoptosis execution enzymes, caspase-3, caspase-7, and caspase-9 in SKOV3 cells treated with KP extract." (PMID 29891015, 2018).
ovarian carcinoma (continued). "In addition, WNT2B can increase the ability of metastasis and chemoresistance of ovarian cancer through the caspase-9/BCL2/BCL-xL pathway and EMT/p-AKT pathways." (PMID 28053597, 2017). "In addition, we observed the reduction of Bcl-2 expression accompanied with elevated levels of cleaved-caspase-9 and cleaved-caspase-3 in ovarian cancer cells treated with PMBPs." (PMID 26539720, 2015). "In order to analyze whether the fenretinide and selenite combination can significantly enhance the activation of caspases on ovarian cancer cells apoptosis, caspase-3 and caspase-9 expression and activity were examined." (PMID 24192821, 2013). "Similarly, ATO induced the reduction of p-AKT and the cleavage of caspase-9 in other ovarian cancer cells, in spite of their differences in chemo-sensitivity." (PMID 21655183, 2011). "Furthermore, NADPH oxidases (NOXs) are recognized as primary sources of intracellular ROS production, and our findings support that hydnocarpin induces apoptosis in ovarian cancer cells by activating the caspase-9-dependent intrinsic apoptotic pathway via NOX-mediated ROS generation." (PMID 40722951, 2025). "Furthermore, it was concluded that assessment of serum caspase-9 and CA 125 marker concentrations may prove useful in the diagnosis of ovarian cancer, but this requires further research." (PMID 33919909, 2021). "Thus, the regulation of caspase-9 may be a novel therapeutic strategy to reverse paclitaxel-induced resistance in ovarian cancer cells." (PMID 29416675, 2018). "Protein expression levels of cleaved caspase-3, caspase-8, caspase-9, and PARP in the A2780 ovarian cancer cells markedly increased, whereas the expression of BID decreased after 20(S)-Rg3 treatment." (PMID 27051448, 2016). "Taken together, these results support the conclusion that hydnocarpin induces apoptosis in ovarian cancer cells primarily through the caspase-9-dependent intrinsic mitochondrial pathway, rather than the extrinsic death receptor pathway." (PMID 40722951, 2025). "There have been no studies to date on the assessment of caspase-9 levels and the evaluation of the expression of this enzyme in patients with ovarian cancer and other gynecological cancers." (PMID 33919909, 2021). "Likewise, we identified that β-sitosterol induced late apoptosis via the activation of apoptotic signals, including cleaved caspase 3 and caspase 9, cytochrome C, BAX, and BAK, in human ovarian cancer." (PMID 34679718, 2021). "In both ovarian cancer cell lines, a significant downregulation of the anti-apoptotic BCL-2 and significant upregulation of cytochrome c and cleaved caspase 9 was observed, corroborating ST09 drug induces intrinsic apoptotic pathway in ovarian cancer cell lines." (PMID 34837026, 2021). "In addition, DAPK1 gene silencing using siRNA prevented the cleavage of caspase-9, caspase-3, and PARP as well as the depolarization of mitochondria membranes induced by treating paclitaxel-resistant ovarian cancer cells with gliotoxin followed by paclitaxel." (PMID 31336860, 2019). "We demonstrated that caspase 9 was highly expressed in carboplatin-resistant ovarian cancer cell lines, but that this was independent of sensitivity to DEBIO 1143." (PMID 30552344, 2018). "Similarly, AEA treatment increased the intracellular levels of ROS and antioxidant NAC treatment inhibited AEA-induced caspase 9-dependent cell death, which suggests that the increase in ROS levels induced by AEA are mediated via the intrinsic apoptosis pathway in human ovarian cancer cells." (PMID 35204176, 2022). "Thus, both ovarian cancer cell lines PA1 and A2780 were treated with 10, 20, and 40 nM of ST09 drug for 48 h and the expression of pro-survival factor BCL-2, pro-apoptotic proteins Bax and Bak, cytochrome C, apoptosome complex protease Apaf-1, and cleaved caspase 9 were evaluated." (PMID 34837026, 2021).
ovarian carcinoma (continued). "Therefore, the activation of caspase-3 and caspase-9 indicates the involvement of the mitochondria-initiated intrinsic apoptotic pathway in Piperine-induced apoptosis in ovarian cancer A2780 cells, rather than the death receptor-dependent extrinsic apoptotic pathway." (PMID 29717031, 2018). "Previous evidence also showed that ovarian cancer cell lines, including the OVCAR-3 cells were detected without the expression of caspase-9, which was in line with the present results." (PMID 27377320, 2016). "Notably, there also appeared to be only marginal increases in the expression of cleaved Caspase-9 and Caspase-7 in both SKOV-3 and SKOV3-TR upon paclitaxel treatment, suggesting that apoptosis may not be the predominant mechanism of inducing cell death in these ovarian carcinoma cells." (PMID 25411964, 2014). "Along these lines, activation of caspase 3, caspase 8, and caspase 9 was induced by SW IV-134, but not by SW43 in different ovarian cancer cell lines." (PMID 24602489, 2014).